CACNA2D2 (calcium voltage-gated channel auxiliary subunit alpha2delta 2)
Description:
The alpha-2/delta subunit of voltage-dependent calcium channels regulates calcium current density and activation/inactivation kinetics of the calcium channel. Acts as a regulatory subunit for P/Q-type calcium channel (CACNA1A), N-type (CACNA1B), L-type (CACNA1C OR CACNA1D) and possibly T-type (CACNA1G). Overexpression induces apoptosis.
Synonyms: KIAA0558; alpha2delta-2; CACNA2D; CASVDD
Tractability: Small molecule: an approved drug acts on it; a high-quality ligand is known; it belongs to a druggable protein family. Antibody: its Gene Ontology location is reachable by antibodies, with high confidence; UniProt predicts a signal peptide or a membrane-spanning region; the Human Protein Atlas places it where antibodies can reach. PROTAC: ubiquitination databases record sites on it; its protein half-life has been measured; a small molecule that binds it is known.
Target class: Auxiliary transport protein; Calcium channel auxiliary subunit alpha2delta family
Gene: Protein-coding gene on chromosome 3 (50,362,613 to 50,504,244, reverse strand). Ensembl gene ENSG00000007402.
Subcellular location: Membrane
Subcellular location (Human Protein Atlas): Cytosol; Flagellar centriole; Mid piece; Plasma membrane
Pathways (Reactome):
Metabolism: Adrenaline,noradrenaline inhibits insulin secretion; Regulation of insulin secretion
Muscle contraction: Phase 0 - rapid depolarisation; Phase 2 - plateau phase
Neuronal System: Presynaptic depolarization and calcium channel opening
Sensory Perception: Sensory processing of sound by inner hair cells of the cochlea
Gene Ontology:
Molecular function: voltage-gated calcium channel activity
Biological process: calcium ion transmembrane transport
Cellular component: plasma membrane; voltage-gated calcium channel complex; membrane
Genetic constraint (gnomAD): Loss-of-function variants: 49 observed, 156.9 expected, observed/expected ratio (o/e) 0.31, 90% interval 0.25 to 0.4. The upper end of that interval is the gene's LOEUF score, 0.4, which puts it in group 1 of 6, group 1 being the genes least tolerant of losing a copy. Missense variants: 1,084 observed, 1,405.9 expected, observed/expected ratio (o/e) 0.77, 90% interval 0.73 to 0.81. Synonymous variants: 543 observed, 558.96 expected, observed/expected ratio (o/e) 0.97, 90% interval 0.9 to 1.04.
Gene-disease validity (ClinGen):
ClinGen rates the evidence that CACNA2D2 causes each of these diseases.
complex neurodevelopmental disorder (autosomal recessive): Moderate. A disorder that involves more than one phenotype associated with the central nervous system, including but not limited to intellectual disability, autism, and seizures (epilepsy).
Homologues: Orthologues: chimpanzee CACNA2D2 (99% identical), macaque CACNA2D2 (99% identical), dog CACNA2D2 (98% identical), mouse Cacna2d2 (97% identical), pig CACNA2D2 (96% identical), rat Cacna2d2 (95% identical), guinea pig CACNA2D2 (92% identical), rabbit CACNA2D2 (84% identical), tropical clawed frog cacna2d2 (74% identical), zebrafish cacna2d2b (60% identical), zebrafish cacna2d2a (29% identical), Drosophila melanogaster stj (25% identical), and 1 more. Paralogues in human: CACNA2D1 (51% identical), CACNA2D4 (29% identical), CACNA2D3 (29% identical), CACHD1 (19% identical).
Diseases named in the same sentence as CACNA2D2 in open-access papers:
CACNA2D2 is named in the same sentence as 72 diseases in open-access papers, as found by Europe PMC text mining. Sharing a sentence is not in itself a finding about the gene and the disease. The quoted sentences say what the papers report.
epilepsy (15 papers, 2011 to 2024). A brain disorder characterized by episodes of abnormally increased neuronal discharge resulting in transient episodes of sensory or motor neurological dysfunction, or psychic dysfunction. "One such subunit is the α2δ-2 protein, encoded by the CACNA2D2 gene, originally associated with a heritable form of epilepsy in the spontaneous α2δ-2 mutant ducky mouse." (PMID 38749701, 2024). "The ducky (du) mutation of Cacna2d2 in mice showed a severe phenotype characterized by cerebellar ataxia, epilepsy, reduced body weight, and premature death." (PMID 37047559, 2023). "Our review has further revealed variants in CACNA1C, CACNA1F, CACNA1I, CACNA2D1 and CACNA2D2 as additional genes related to epilepsy." (PMID 33985586, 2021). "Two distinct splice site mutations in CACNA2D2, for example, lead to the truncation of the protein, causing epilepsy, dyskinesia, and cerebellar atrophy in one patient, whereas the other mutation is associated with congenital ataxia." (PMID 30683685, 2019). "CACNA2D1 and CACNA2D2 are both associated with epilepsy and ID, while CACN2D3 has been recently implicated in ASD." (PMID 28713243, 2017). "Although hilar mossy cell loss is a prominent characteristic of many mouse models of epilepsy, we found that not only was the mossy cell population intact within the dentate hilus of CACNA2D2 KO mice, but there was a small statistically significant increase in mossy cell density in KO mice." (PMID 38749701, 2024). "This is insofar surprising as neurological disorders have been linked to aberrant α2δ subunit expression in humans: mutations in CACNA2D1 and CACNA2D2 with epilepsy, CACNA2D3 is a potential risk gene for autism spectrum disorders, and all three genes with schizophrenia." (PMID 33679366, 2021). "The chromosome 3 region spans 159 genes, including neuronal development genes SEMA3F and SEMA3B, and epilepsy-associated genes NPRL2, CACNA2D2, and CYB561D2." (PMID 35190550, 2022). "Our review has highlighted CACNA1C, CACNA1F, CACNA1I, CACNA2D1 and CACNA2D2 as additional genes for epilepsy, and CACNA2D1 for autism spectrum disorder." (PMID 33985586, 2021). "CACNA2D2 is an important epilepsy-related calcium channel protein involved in small molecule ligand interactions as well as neuronal cell death pathways VWF is involved in inflammation, seizures, neurodegeneration, and blood brain barrier permeability." (PMID 32823271, 2020). "Another prominent epilepsy related ion-channel protein found in this analysis is CACNA2D2, a calcium channel protein involved in small-molecule ligand interactions as well as neuronal cell death pathways." (PMID 32751954, 2020). "The role of voltage-gated channels in the activity of neuronal excitability indicates that mutations in Ca2+ channel genes CACNA1A, CACNA1H, CACNA2D2, and CACNB4 might be associated with the occurrence of epilepsy." (PMID 38383918, 2024). "Recent evidence suggests that the effects of CACNA2D2 on axonal growth and elongation as well as on synaptic formation are inhibited by pregabalin, a drug which targets the α2δ-2 subunit and which is used in several neurological conditions, including epilepsy." (PMID 33390903, 2020).
Epileptic encephalopathy (10 papers, 2013 to 2025). A condition in which epileptiform abnormalities are believed to contribute to the progressive disturbance in cerebral function. "There are several reports that the defect in CACNA2D1 or CACNA2D2 causes developmental and epileptic encephalopathies, hypotonia, and severe cerebellar ataxia, symptoms of which can be also observed in IGDs, including PIGA deficiencies." (PMID 38225934, 2024). "Both the patients with Met2630Ile and Gly2136Asp had homozygous CACNA2D2 variants, which was a disease‐causing gene of early‐onset epileptic encephalopathy/global developmental delay and potentially explained the epileptic encephalopathy." (PMID 34951123, 2022). "It is worth remarking, however, that biallelic variants in CACNA2D2 are detected in an early onset form of epileptic encephalopathy, which shares some clinical features with CLN1 disease." (PMID 33390903, 2020). "To date, there have only been two reports of individuals with early-infantile epileptic encephalopathy due to CACNA2D2 mutations." (PMID 30410802, 2018). "Contribution to epileptic encephalopathy (EE) of mutations in CACNA2D2, encoding α2δ-2 subunit of Voltage Dependent Calcium Channels, is unclear." (PMID 24358150, 2013). "Several genes encoding VGCC subunits have been associated with epileptic encephalopathy, including CACNA1A, CACNA1C, CACNA1E, CACNA2D1, and CACNA2D2." (PMID 39161180, 2025). "Recently, a homozygous CACNA2D2 (Calcium Channel, Voltage Dependent, α2δ subunit 2; MIM 607082) mutation was identified in a family with 3 siblings, offspring to consanguineous parents, who presented with early-onset epileptic encephalopathy and global developmental delay." (PMID 24358150, 2013).
lung carcinoma (7 papers, 2007 to 2025). "Moreover, expression deficiency of CACNA2D2, which encodes for a new subunit of the Ca2+-channel complex, has been postulated as a possible link in the pathogenesis of lung cancer, similar to M1AP." (PMID 36980682, 2023). "CACNA2D2 is a subunit of the Ca2+ channel complex that was initially identified as a tumor suppressor gene located in the lung cancer homozygous deletion region of chromosome 3p21.3." (PMID 39858622, 2025). "A reduced expression of CACNA2D2 has been described in lung cancer, gliomas, nasopharyngeal, head and neck squamous cell carcinoma and cervical carcinoma." (PMID 28460460, 2017). "Mechanistically, colon cancer cells treated with calcium channel agonist induced apoptosis, and overexpression of CACNA2D2 in lung cancer cell lines induced apoptosis through elevating intracellular Ca2+ level." (PMID 28127114, 2017).
Ataxia (6 papers, 2022 to 2024). Ataxia refers to impaired coordination of voluntary muscle movement. "Inhibition of Dpp4 showed a neuroprotection effect in diabetic mouse brain, and the Cacna2d2 mutant mice were affected with cerebellar neuro-degeneration associated with ataxia and seizures." (PMID 36831877, 2023).
Cerebellar atrophy (6 papers, 2013 to 2026). Cerebellar atrophy is defined as a cerebellum with initially normal structures, in a posterior fossa with normal size, which displays enlarged fissures (interfolial spaces) in comparison to the foliae secondary to loss of tissue. "Genetic analysis identified a private homozygous missense variant in the bovine CACNA2D2 gene (XP_024839037.1:p.(Cys395Arg)), which is linked to neurological disorders in other species, including a form of cerebellar atrophy in humans." (PMID 41873845, 2026). "Individuals with biallelic CACNA2D1 or CACNA2D2 variants all have corpus callosum hypoplasia, while patients with CACNA2D1 variants show progressive cerebral atrophy whereas subjects harbouring CACNA2D2 variants have cerebellar atrophy." (PMID 35293990, 2022). "In the brain, the protein encoded by CACNA2D2, α2δ-2, is mostly abundant in the cerebellum and particularly in Purkinje cells, consistent with the patient’s cerebellar atrophy." (PMID 24358150, 2013). "Mutations in CACNA2D2 have been associated with developmental and epileptic encephalopathy (DEE) and cerebellar atrophy." (PMID 39161180, 2025).
non-small cell lung carcinoma (6 papers, 2013 to 2024). A group of at least three distinct histological types of lung cancer, including non-small cell squamous cell carcinoma, adenocarcinoma, and large cell carcinoma. "Moreover, MIR210HG was identified as prognostic marker of colorectal cancer and shown to promote the proliferation and invasion of non-small-cell lung carcinoma via inhibiting the expression of CACNA2D2 by recruiting DNMT1." (PMID 33375322, 2020). "A previous study has reported that CACNA2D2 could elevate intracellular Ca2+ level in non-small cell lung cancer cells." (PMID 23560067, 2013). "In addition, an elevated intracellular Ca2+ level was detected when CACNA2D3 was introduced into cells, which was similar to the results of CACNA2D3 in gastric cancer cells and CACNA2D2 in non-small cell lung cancer cells." (PMID 23560067, 2013). "One report indicated that CACNA2D2 could mediate apoptosis in non-small cell lung cancer cells." (PMID 23560067, 2013). "The lncRNA MIR210HG promotes the proliferation and invasion of non-small cell lung cancer by binding to DNMT1 directly, thereafter upregulating methylation of the CACNA2D2 promoter." (PMID 38784389, 2024).
colorectal cancer (3 papers, 2017 to 2023). A primary or metastatic malignant neoplasm that affects the colon or rectum. "Studies have shown that CACNA2D2 plays an important role in several cancers, including endometrial cancer, colorectal cancer, and NSCLC." (PMID 36975430, 2023). "CACNA2D2 mRNA expression was found to be significantly decreased in colorectal carcinomas when compared to their corresponding matched normal colon tissues for 33 of 54 samples (61%) (p-value < 0.0001)." (PMID 28460460, 2017).
glioma (3 papers, 2017 to 2021). A benign or malignant brain and spinal cord tumor that arises from glial cells (astrocytes, oligodendrocytes, ependymal cells). "Previous reports showed that miR-1231 could target EGFR and CACNA2D2 directly in glioma and embryonic kidney cells." (PMID 34650036, 2021).
Arrhythmia (2 papers, 2018 to 2023). Any cardiac rhythm other than the normal sinus rhythm. "Voltage-dependent calcium channel subunit alpha2delta2 (CACNA2D) is known to be responsible for regulating calcium transportation and signal responses in cardiomyocytes, and it has been reported that miR-1231 aggravates arrhythmia by targeting CACNA2D2." (PMID 37106699, 2023).
breast carcinoma (2 papers, 2021). "Previous findings showed that CACNA2D2 promote tumorigenesis by stimulating cell proliferation and angiogenesis in prostate and breast cancer while CACNA1E was upregulated in lung squamous cell carcinoma and wilms tumor." (PMID 34299042, 2021).
cervical carcinoma (2 papers, 2017 to 2022). A carcinoma arising from either the exocervical squamous epithelium or the endocervical glandular epithelium. "Prognostic implications of CACNA2D2 have been reported in head and neck squamous cell carcinoma and cervical carcinoma." (PMID 28460460, 2017).
coronary heart disease (2 papers, 2020 to 2023). "For example, CACNA2D2 is involved in pathways related to T2D-associated coronary heart disease, cardiomyopathy, cardiac muscle contraction." (PMID 37679740, 2023).
dilated cardiomyopathy (2 papers, 2020 to 2025). Cardiomyopathy which is characterized by dilation and contractile dysfunction of the left and right ventricles. "CACNA2D2 and IGF1 are associated with dilated cardiomyopathy pathway according to KEGG pathway enrichment analyses." (PMID 33392258, 2020).
lung squamous cell carcinoma (2 papers, 2021 to 2025). "Furthermore, high expression of CACNA2D2 was correlated with poor survival in lung squamous cell carcinoma patients, contrasting with findings in lung adenocarcinoma." (PMID 39858622, 2025).
prostate carcinoma (2 papers, 2021 to 2022). A carcinoma that arises from epithelial cells of the prostate gland. "We identified ancestry-linked germline and somatic mutation frequencies in DNA damage repair genes (BRCA1, BRCA2, APC, and ATM), as well as three novel prostate cancer–associated genes (CACNA2D2, SYNE1, and ADAMTS2)." (PMID 36922933, 2022). "Compared with noncancerous prostate tissue, CACNA2D2 is expressed higher in prostate cancer tissue and can increase tumor proliferation and angiogenesis." (PMID 36922933, 2022).
atrial fibrillation (1 paper, 2017). A disorder characterized by an electrocardiographic finding of a supraventricular arrhythmia characterized by the replacement of consistent P waves by rapid oscillations or fibrillatory waves that vary in size, shape and timing and are accompanied by an irregular ventricular response. "This extended gene network contained a number of transcription factors (Tbx5, Hand2, Fhl2, and Gata4) and ion/calcium handling genes (Ank2, Cacna2d2, Scn5a, Kcnd2, Kcnj5, Myoz2, Casq2, Csrp3, and Gja3) of interest in the context of atrial fibrillation." (PMID 28720711, 2017).
B-cell neoplasm (1 paper, 2018). A group of heterogeneous lymphoid tumors generally expressing one or more B-cell antigens or representing malignant transformations of B-lymphocytes. "FISH analyses narrowed one breakpoint down to region 3p21 located between the genes CACNA2D2 and CACNA2D3, and the other breakpoint to the IGH locus at 14q32 which is recurrently altered in B-cell neoplasms." (PMID 30680064, 2018).
depression (1 paper, 2016). "The decreased expressions of mRNAs in CUMS-induced depression mice include Slc6a11, Hap1, Gad1, Gad2, Gng4, Slc32a1, Doc2g, Slc32a1, Magel2, Prkcd, Ngfr, Dusp1, Th, Itih3, Cacna2d2, Arc, Mbp, Peg10, Fos, and so on." (PMID 27427907, 2016).
diabetic cardiomyopathy (1 paper, 2024). Diabetic cardiomyopathy is a disorder of the heart muscle in people with diabetes. "We constructed a diagnostic model of DCM, and OXCT1, CACNA2D2, BCL7B, EGLN3, GABARAP, and ACADSB were potential biomarkers, which may provide new insights for improving the ability of early diagnosis and treatment of diabetic cardiomyopathy." (PMID 38469146, 2024). "We found diagnostic and predictive biomarkers of type 2 DCM consisting of OXCT1, CACNA2D2, BCL7B, EGLN3, GABARAP, and ACADSB, which may reduce the difficulty of early prediction of diabetic cardiomyopathy, and lay a foundation for prospective research." (PMID 38469146, 2024).
Dystonia (1 paper, 2018). An abnormally increased muscular tone that causes fixed abnormal postures. "In fact, virtually all genes associated with dystonia in spontaneous mutants (tottering, stargazer, ophisthotonus, ducky, lethargic, waddles, and wriggle) are involved in Purkinje cell Ca2+ signaling (Canca1a, Cacng2, Itpr1, Cacna2d2, Cacnb4, and Pmca2)." (PMID 29770609, 2018).
Hypertension (1 paper, 2023). The presence of chronic increased pressure in the systemic arterial system. "In 2018, the GWAS catalog found seven candidate genes with an established pathophysiological role in hypertension, namely ACE1, ACE2, ADRB1, ADRB2, MME, CACNA2D2, and UMOD." (PMID 36902588, 2023).
lung adenocarcinoma (1 paper, 2025). A carcinoma that arises from the lung and is characterized by the presence of malignant glandular epithelial cells. "The level of CACNA2D2 is significantly higher in the TSPX-high lung adenocarcinoma samples, as compared with TSPX-low lung adenocarcinoma samples." (PMID 39858622, 2025). "Taken together, our results suggest that TSPX may suppress the development and/or progression of lung adenocarcinoma by downregulating AREG, BIRC3, DKK1, EREG, FOSL1, MYC, and PLAU, which could exacerbate lung adenocarcinoma, and upregulating the tumor suppressor CACNA2D2." (PMID 39858622, 2025).
lymph node metastasis (1 paper, 2022). "After taking the intersection with GSE101448, 13 genes (CDK5R2, SYT7, CACNA2D2, etc.)which might prevent lymph node metastasis were further selected." (PMID 36344976, 2022).
melanoma (1 paper, 2022). A malignant, usually aggressive tumor composed of atypical, neoplastic melanocytes. "Six targets—S100A9, FLG, SAMMSON, LY6D, CACNA2D2, and HES1—were found to have variable expression in different melanoma cell lines, so they could not be validated as GLI targets in melanoma." (PMID 36139698, 2022).
nicotine dependence (1 paper, 2024). Physical and psychological dependence on nicotine. "Other members of the α2δ family, such as CACNA2D2, are also associated with nicotine dependence, smoking initiation, and cigarette consumption." (PMID 38338915, 2024). "Like CACNA2D2 and CACNA2D3 have been reported as GWAS candidates associated with nicotine dependence, CACNA2D1 has been involved in increased presynaptic NMDAR activity associated with hyperalgesia following chronic morphine." (PMID 38338915, 2024).
varicocele (1 paper, 2022). A condition characterized by the dilated tortuous veins of the spermatic cord with a marked left-sided predominance. "The calcium channel, voltage-dependent, alpha 2/delta subunit 2 (CACNA2D2) regulates calcium current density and is highly expressed in the testis and has been found under expressed in varicocele patients." (PMID 35205102, 2022).